CD4 (CD4 molecule)
Diseases named in the same sentence as CD4 in open-access papers (continued):
Sharing a sentence is not in itself a finding about the gene and the disease.
infection (continued). "MZB may be directly involved in HIV-1 replication via trans infection of tissue-resident CD4 + T cells." (PMID 33214610, 2020). "The infection of humans with Orientia leads to a loss rather than an increase in peripheral CD4+ T cells including regulatory T cells (Tregs) in the acute phase of infection, while activated CD8+ T cells increase." (PMID 33091016, 2020). "Interestingly, Vγ9Vδ2 cell depletion occurs very early during the infection, and correlates with viral load and CD4+ T cell depletion." (PMID 33348583, 2020). "Nonetheless, CD4+ cells are crucial to multiple functions in an optimal immune system and immunological memory, and routine CD4+ cell count is the standard of care assessment for HIV+ patients to determine infection progression and response to ART, despite expected inter-individual differences." (PMID 32637718, 2020). "In early infection, the CD4+ memory T-cell is the primary HIV-1 target cell." (PMID 32985522, 2020). "However, in the ECHO cohort, pre-infection frequency of CD161+ CD4+ T cells in the peripheral blood were higher in participants that remained uninfected during the course of the study, compared to those that became HIV-infected." (PMID 33322496, 2020). "Interestingly, CD4+ T cell polarization into Tfh happens with IFN exposure at early stages of the infection, while exposure at delayed stages promotes differentiation into Th1 cells." (PMID 32612666, 2020). "Similarly, in the thymus, the percentage of CD8+ T lymphocytes and the ratios of CD4+/CD8+ in the infection group is significantly up- and down-regulated, respectively, at 14 DPI (p < 0.01 and p < 0.05) compared with the control group." (PMID 31963363, 2020). "According to the rule that the CD4+ T-cell count was reduced by an average of 50/μL per year, the infection time of ≥8 years accounted for 25.2% (180/714), 5–8 years accounted for 23.2% (166/714), 3–5 years accounted for 18.3% (131/714), and <3 years accounted for 33.2% (237/714)." (PMID 32197326, 2020). "These events include dendritic cell and macrophage infection; immune target cell dysregulation; antigen presentation to CD4+ T cells; involvement of B cells and antibody responses; infection of parenchymal cells; and killing of infected cells by CTL or NK cells." (PMID 32098330, 2020). "Significantly higher levels of IFN-γ and TNF-α cytokine-secreting CD4 T cells were generated upon M2e in vitro stimulation of the airway BAL cells from all LAIV-vaccinated mice at day 5 post-challenge infection compared to naïve mice as determined by flow cytometry ICS analysis." (PMID 33153089, 2020). "Another possibility for HIV detection in the periphery is the escape of virus (free or loosely bound to astrocyte cell membrane) at the time of astrocyte transplantation into circulation and subsequent infection of CD4+ T cells in spleen and lymph nodes post huPBMC reconstitution." (PMID 32525948, 2020). "However, the diagnosis probabilities/rates keep at a very low level, and there are still a large number of infections undiagnosed, most of which have a large probability to be identified at late CD4 stage." (PMID 32532238, 2020). "The ability of CD4+ T cells to generate memory is a critical feature of their biology and is thought to allow the immune system to respond more rapidly and effectively to a previously encountered infection." (PMID 32983171, 2020). "Supporting the importance of cell state, Siliciano and colleagues showed that latency is an unfortunate consequence of infection of CD4+ T cells within a narrow time window after activation in which transcriptional reprogramming during EMT renders CD4+ T cells permissive for latency." (PMID 32443452, 2020). "Decreased frequency of CD8+ CD45RA+ and CD4+ CD45RA+ T cells have never been associated with acute rejection but with infection in older kidney recipients (> 60 years)." (PMID 32038663, 2020).
infection (continued). "Importantly, we showed that MVA infection significantly downregulated CCR5 in CD4+ T cells, CD8+ T cells, B cells, and three different DC populations." (PMID 33013882, 2020). "We therefore considered the possibility that SAMHD1 may also restrict infection in tissue-derived CD4+ T cells." (PMID 32353080, 2020). "In infected humans, CMV induces an inflation of both the CD4+ and CD8+ effector-memory T cells, followed by a dramatic shrinkage of TCR repertoire, as such may add to the increased risk of infections as well as CVD in healthy and ESRD individuals." (PMID 32660510, 2020). "However, the infection rate of macrophages, the major target cells for viral replication inside the brain, is significantly smaller than that of CD4+ T cells." (PMID 33211686, 2020). "Recent studies have rehighlighted the importance of antigen-independent bystander activation of CD4+ T cells in infection clearance and autoimmune pathogenesis, suggesting the existence of a distinct innate-like immunological function performed by conventional T cells." (PMID 32859954, 2020). "Following intravenous infection with an attenuated strain of Lm, we found that total antigen-specific CD4+ T cells responded more robustly in secondary compared with primary infection, reaching near-peak levels in secondary lymphoid organs (SLOs) and the liver by three days post-infection." (PMID 32983171, 2020). "However, the expanded populations on day 10 after infection enabled robust phenotypic analysis of epitope-specific CD4+ T cells in both blood and BAL." (PMID 31815739, 2020). "In other examples of infection, there are important roles for antigen-specific CD4 T cells." (PMID 32462053, 2020). "Furthermore, it has been well established that memory antigen-specific CD4+ T cells are able to clear C. trachomatis infection during secondary infection." (PMID 33091023, 2020). "(g) DCs can also mediate trans-infection of other target cells, namely CD4+ T cells." (PMID 33212766, 2020). "While we find relative discordance of responses in our study comprising individuals at 4 months after infection, other reports of concordance either between S1 Ab and neutralization or between neutralization and spike CD4 T cell responses tended to analyze within the first weeks after infection." (PMID 33361161, 2020). "Furthermore, prior infection with Mp increased the number of neutrophils in BALF after the reinfection of DBA/2 mice through an Mp-specific CD4+ T cell-dependent mechanism." (PMID 33520736, 2020). "However, the CD4+ T cell number mildly increased after infection in the CD83 KO mice; however, the total number of cells in the CD83 KO mice was still much lower compared to the wild type mice." (PMID 33302987, 2020). "In addition, DMT alone induced much more levels of CMFO-specific IFN-γ+ CD4+ TEM cells and IL-2+ CD4+ TCM cells in the spleen than MTO control mice before infection." (PMID 32953889, 2020). "To further our understanding of the phenotype of the conserved TRBV3 response observed during the acute phase of a P. chabaudi infection, we undertook single-cell RNA sequencing of FACS sorted CD3+ CD4+ splenocytes from two mice at day 7 post-infection with MT parasites." (PMID 33329568, 2020). "Here, we show that in adenoids of 102 infants and children similar frequencies of naïve, effector, and memory T-cells were accumulated, whereby history of suffering from subsequent infection symptoms resulted in lower frequencies of CD4+ and CD8+ T-cells co-expressing several cytokines." (PMID 32849561, 2020). "When we analyzed proportions of splenic T cells two weeks post infection with L. interrogans we found increased populations of CD4+ effector T cells in infected versus uninfected mice in WT, huTLR4 and muTLR4Lps-del which was consistent with our previous observations in C3H-HeJ mice." (PMID 33519799, 2020).
infection (continued). "This increase in NK cells appeared to be related to infection because, at baseline, there were minimal differences in the frequency or numbers of NK cells as well as in naïve and effector/effector memory CD4+ T cells or their state of activation at baseline as assessed by CD69 expression." (PMID 32153566, 2020). "Nevertheless, it is not well understood the role played for CD4+ Treg in human ANDV infection." (PMID 32984065, 2020). "That the associations in LTBI are independent of CD4 T cells is substantiated by reduced hazards of these infections in a CD4 cell time-updated time-to-event analysis." (PMID 33284802, 2020). "Consequently, while infections seem to be responsible for reduced frequencies of IFNγ+TNFα+ co-expressing CD4+ T-cells in the first 2 years of life, an increase of triple producers is merely due to development." (PMID 32849561, 2020). "Interestingly, CD8 depletions altered infection of different lineages compared to CD4 depletions, but showed a similar dependence on the baseline level of CD4+ T cells." (PMID 33075105, 2020). "Interestingly, high levels of CD4+ T cell populations were observed in the MSP-9 VLP-immunized group after the challenge infection (* p < 0.05)." (PMID 32751598, 2020). "In comparison, Ag85B-specific CD4 T cells were ~1% of the activated CD4 T cells, with a relatively more delayed accumulation after infection, while ESAT6 tetramer-binding cells constituted more than 5% of activated CD4 T cells, with a relatively early increase early after infection." (PMID 33193338, 2020). "CD4+ T cells were quickly found to be primary targets during productive infection." (PMID 32194526, 2020). "As a result of the infection, there is a strong CD4+ TH1, CD8+, and neutralizing antibody response." (PMID 32499988, 2020). "Similarly, intravenous or subcutaneous infection of C57BL/6 mice as well as subcutaneous infection of BALB/c mice with O. tsutsugamushi Karp leads to a much stronger increase of CD8+ T cells than CD4+ T cells within the first 14 days after infection." (PMID 33091016, 2020). "Moreover, Th2 response and Bcl6 expression in CD4+ T cells were also increased in vivo by blocking PD-L1 after infection, although the hepatic pathology was slightly influenced." (PMID 32197642, 2020). "Depending on the donor, CD4+ T cells with reduced YTHDF3 expression were between 2.5 and 7-fold more susceptible to infection compared to CD4+ T cells electroporated with the non-targeting control." (PMID 32053707, 2020). "More attentions should be paid to identify infections at their early CD4 stages." (PMID 32532238, 2020). "While there are limited studies on the effect of Moringa on T cell activation, the current report shows that mice given a low dose of Moringa for 3 weeks after infection had increased numbers of activated CD4+ T cells in the spleens in response to the Plasmodium infection." (PMID 32033605, 2020). "In vitro infection assays showed transitional memory (TM) and effector memory (EM) CD4+ T cells were more frequently infected (median: 46% and 25% of total infected CD4+ T cells respectively) than naïve, stem cell memory, central memory and terminally differentiated cells." (PMID 32762760, 2020). "This modelling approach can link the CD4 data at the individual level to the surveillance data at the population level to some what and make a relatively accurate estimation on new infections and undiagnosed infections." (PMID 32532238, 2020). "CD4 T cell-replete mice infected with attenuated Se-2W had significantly lower pathogen burdens after secondary virulent Se-2W infection compared to the CD4 T cell-depleted mice, and had pathogen burdens comparable to that seen in naïve mice only infected with virulent Se-2W." (PMID 32903436, 2020).
infection (continued). "Alternatively, if HIV-infection is left untreated while CD4 T cells are responding to either chronic persistent infections such as those caused by CMV or EBV or recurrent infections such as influenza, then reservoir cells might be specific for those pathogens." (PMID 33228686, 2020). "They enhance infection in cell lines, primary CD4+ T cells, and primary macrophages." (PMID 32726944, 2020). "Thus, it is impossible to compare the estimated number of new infections and the real new infections, so is the CD4 level of new infections." (PMID 32532238, 2020). "Immunization with purified A. marginale outer membranes can induce complete protection against infection by homologous strains, probably due to CD4+ T-lymphocyte-mediated Interferon gamma (IFN-γ) release and secretion of immunoglobulin G (IgG)-2 antibodies against outer membrane protein epitopes." (PMID 33233869, 2020). "Thus, we evaluated IL-17- and IL-22-producing CD4+ T cells at 6 h (for immediate early) and (24 h for early response) post-infection in the lungs of mice immunized with PBS versus Trivalent-FP." (PMID 32340134, 2020). "Low CD4 counts were correlated with infection by EBV (P = .010) and HHV‐7 (P = .044)." (PMID 31621089, 2020). "Importantly, in comparison to the CD8+ compartment the CD4+ compartment behaves differently in the way that age and infections impact the formation of cytokine co-producers." (PMID 32849561, 2020). "After infection, IL-2+ CD4+ T cells and TCM cells were dominant in the spleen of all groups." (PMID 33117374, 2020). "Instead, the overall increase in polyfunctionality over the first year of infection (12M-1M) was significantly correlated with CD4 counts, highlighting the presence of more functional antibodies in the setting of preserved CD4 cell function and help." (PMID 32849622, 2020). "This is in contrast to production of IFN-γ and IL-10 that correlate with infection, suggesting that different CD4+ve subsets may be activated by C. abortus infection in sheep." (PMID 32487248, 2020). "A robust CD4+ Th1 response is essential during the systemic infection phase with S. Typhimurium." (PMID 33604308, 2020). "Such sequentially biphasic CD4+ cell response appears during primary parasite infection." (PMID 31612155, 2019). "Analysis of serum on day 10 post-infection revealed that, in contrast to the findings with mice infected RO, depletion of CD4+ T cells significantly reduced the titers of ZIKV-specific IgM and IgG as well as the anti-ZIKV neutralizing Ab activity compared with control mice." (PMID 30677097, 2019). "CD4+ T cells, after being activated and differentiated into distinct effector subtypes (ie, Th1 cells, Th2 cells, and Th17 cells), play a central role in activating macrophage and dendritic cells during initial infections with parasites, bacteria, or viruses." (PMID 31574798, 2019). "However, infection induces a robust Th1 CD4 T cell response, which features expression of the transcription factor T-bet and production of effector cytokines IFN-γ, TNF-α, and interleukin (IL)-2." (PMID 31382545, 2019). "Consistent with the results of bacterial RNA quantitation, CD4 T cells specific for Ag85B are activated in the lungs between 2 and 3 weeks after infection of mice, but their activation markedly decreases concurrent with decreased bacterial expression of the fbpB gene." (PMID 31015327, 2019). "In addition, HIV infection and depletion of CD4+ T cells, with preferential infection of HIV-specific CD4+ T cells, exacerbates immune impairment by providing insufficient help for HIV-specific CD8+ T cells." (PMID 31552045, 2019). "Although animals of both species showed decreases in CD8+ T-cell frequency early in infection, with an increase in PD1+ CD8+ T-cell frequency later in infection, only SHFV-infected patas monkeys showed an increase in CD4+ T-cell numbers largely throughout infection." (PMID 30650570, 2019).
infection (continued). "PX-12 also affects oxidoreductase activity and we therefor decided to test if PX-12 interferes with the early infection event by utilizing an infectivity assay consisting of TZM-bl (HeLa/CD4/CXCR4/CCR5) cells which contain a luciferase gene that is under the control of the HIV-1 promoter." (PMID 30948772, 2019). "CD4 T cells play a cardinal role in maintaining enduring protection against infection." (PMID 30894125, 2019). "Furthermore, transfer of small numbers of CD4 T cells from the lungs of convalescent or wP-immunized, but not from the spleen of wP- or aP-immunized mice, conferred some protection against infection of naïve mice with B. pertussis." (PMID 30866771, 2019). "It was shown that CD4+ differentiation during chronic or prolonged antigenic stimulation in the context of infection skews CD4+ T cells toward a T follicular helper (TFH) cell lineage which may account for the loss of TH1 cell cytokine production." (PMID 31379821, 2019). "The relative levels of infectivity were calculated for cell culture infection in 293T/CD4/X4 cells." (PMID 31027334, 2019). "We find that the expression of integrin αvβ8 on dendritic cells (DCs), previously shown to be key in activating TGFβ and maintaining Tregs during intestinal homeostasis, is essential for the induction of TGFβ signalling in CD4+ T-cells and the generation of Th17 cells during infection." (PMID 30998782, 2019). "Additional studies were performed to determine whether the anti-CD235a antibody can interfere with HIV-1 (R5-tropic) trans-infection of CD4+ T cells by CECs or RBCs." (PMID 31772057, 2019). "Even if the adaptive response is quite limited in IPA, increased stimulation of the CD4+ T-lymphocytes population at time of the sacrifice (72 h) is consistent with the usual kinetics of recruitment of such cells during natural recovery from infection." (PMID 30972049, 2019). "We hypothesize that since females naturally have higher levels of CD3+ and CD4+ T cells, perhaps there were enough circulating T cells in the PBMCs to control the infection." (PMID 31477151, 2019). "The vaccinated NHPs showed profound control of acute infection (2/6 completely controlling infection following 10 challenges) and all vaccinated animals had long-term immunological benefits such as reduced rectal CD4+ T-cell depletion and highly limited CD8+ T-cell hyperactivation." (PMID 31126293, 2019). "However, there was a trend of reduced TNF production at least by CD4+ and DN DC subsets upon infection with the PSM-secreting S. aureus USA300 WT strain." (PMID 31134074, 2019). "There are several hypotheses to explain the reduced infection of CD4+ T-lymphocytes, one of which is the capacity of SEA and rω-1 exposed DCs to induce regulatory T (Treg) cells." (PMID 31487324, 2019). "Because activated CD4+ T cells are the primary targets of HIV‐1, virus infection induces inflammation and immune activation that enhances susceptibility to HIV‐1 infection by attracting target cells to the site of infection." (PMID 31339004, 2019). "Since our data indicate that CD4+ T cells do not contribute to ZIKV clearance early (day 7) after primary infection via the RO route, we asked whether memory CD4+ T cells, which become detectable at days 21–28 after primary infection, might be more effective." (PMID 30677097, 2019). "In particular, neutralizing antibodies, induced by ZIKV vaccines, may block infection, while CD4+ and CD8+ T cells secrete IFN-γ, IL2 (Th1), IL-4, and IL-5 (Th2) cytokines to further promote antibody production or directly kill infected cells." (PMID 31717890, 2019). "While the mechanism for this additional local protection has yet to be determined, we demonstrate that delivery of BCG mucosally recruits CD4+ T cells from the periphery to the lung parenchyma, increasing the total number of cells present at the primary site of infection." (PMID 30446726, 2019).